IL1B (interleukin 1 beta)
Diseases named in the same sentence as IL1B in open-access papers (continued):
Sharing a sentence is not in itself a finding about the gene and the disease.
aortic stenosis (2 papers, 2023 to 2025). Aortic valve stenosis is a aortic valve disease caused by the incomplete opening of the aortic valve. "IL-1β induces inflammatory responses in human aortic valve interstitial cells (AVICs) and is involved in the pathogenesis of aortic stenosis." (PMID 40305201, 2025).
aortitis (2 papers, 2019 to 2023). Inflammation of the aorta. "However, it remains unclear which types of cells produce IL-1Ra and IL-1β in the lesions of aortitis in Il1rn−/− mice." (PMID 31745167, 2019). "DC-derived IL-1β and macrophage-derived TNF are thought to subsequently activate Th17 cells to induce IL-17, contributing to development of aortitis in Il1rn−/− mice." (PMID 31745167, 2019). "It was reported that the development of aortitis was diminished in Il1r1−/−Il1rn−/− mice and Tnfa−/−Il1rn−/− mice, whereas it was normal in Il6−/−Il1rn−/− mice, indicating that IL-1α and/or IL-1β, and TNF are crucial for development of aortitis in Il1rn−/− mice." (PMID 31745167, 2019).
arterial disease (2 papers, 2022). "Concomitant arterial disease in mixed venous-arterial ulcers did not influence the levels of EGF, FGF-2, IL-1α, IL-1β, IL-6, PDGF, TGF-β1 and TNF-α in one study." (PMID 35742965, 2022).
Arterial stenosis (2 papers, 2022 to 2023). Narrowing or constriction of the inner surface (lumen) of an artery. "It was suggested that SAH, IL-1β, Hcy, TNF-α, BDNF were positively correlated with the number of coronary artery stenosis vessels(r = 0.421, 0.533, 0.301, 0.265, 0.678, P = 0.016、0.009、0.023、0.036、0.004)." (PMID 35282820, 2022).
arteritis (2 papers, 2017 to 2022). An inflammatory process affecting an artery. "On the other hand, IL-1α/β-KO mice did not develop CAWS-induced arteritis 39, confirming the direct pathogenic role of IL-1β in CAWS-induced arteritis." (PMID 35173530, 2022).
B-cell lymphoma (2 papers, 2023 to 2024). "Given the B-cell-derived origin of plasma cells as well as the pathways shared in the pathogenesis of lymphoid and plasma cell malignancies, targeting IL-1β signaling presents a potential therapeutic approach for B-cell lymphomas." (PMID 38397043, 2024). "Eugenol may have an apoptotic effect by reducing cyclooxygenase-2 (COX-2), B-cell lymphoma, and interleukin-1 beta production, and by increasing the activity of caspase-3 and caspase-9 caspase proteins." (PMID 37205310, 2023).
bladder overactivity (2 papers, 2025). "Conditions like overactive bladder have been linked to systemic inflammation involving cytokines such as IL-1β and NLRP3 or oxidative stress parameters like increased MDA levels or depleted antioxidant levels." (PMID 40001926, 2025). "Increased responsive proinflammatory mediators (NGF, ICAM-1, COX-2, IL-1β, IL-6, TNF-α) likely contribute to bladder overactivity." (PMID 39941129, 2025).
bladder tumor (2 papers, 2019 to 2022). "Furthermore, additional experiments suggest radiation-activated NFκB signaling might stimulate bladder tumor progression by regulating the expression of IL-1β." (PMID 31766169, 2019). "Indeed, we observed upregulation of HIF-1α in human bladder tumor samples, together with VEGF (angiogenesis) and IL-1α and IL-1β (inflammation), which are indicative of poor prognosis in cancer and aggressiveness." (PMID 36233054, 2022).
Blau syndrome (2 papers, 2020 to 2022). Blau syndrome (BS) is a rare systemic inflammatory disease characterized by early onset granulomatous arthritis, uveitis and skin rash. "However, more recent in vitro studies using PBMCs or monocytes derived from patients with Blau syndrome showed reduced NF-κB activation and cytokines such as IL-1β in response to MDP, suggestive of a loss-of-function or “exhausted phenotype” in myeloid cells." (PMID 33106495, 2020).
blepharitis (2 papers, 2022 to 2023). Inflammation of the eyelids near the eyelashes. "Studies have reported that levels of chronic inflammatory cytokines such as IL-1β, IL-6, TNF-α and IFN-γ are higher in depressed patients, suggesting a similarity in the mechanism of blepharitis development." (PMID 35372440, 2022).
Blindness (2 papers, 2021 to 2023). Blindness is the condition of lacking visual perception defined as a profound reduction in visual perception. "It has also been suggested that during infection, assembly of the inflammasome via IL-1β attracts inflammatory mediators and in the process of controlling the pathologic effect, it in turn causes a collateral damage to the host tissue resulting in partial or permanent blindness." (PMID 35046947, 2021).
bovine tuberculosis (2 papers, 2021 to 2025). "AIM2 upregulation by rFIP-nha was in line with observations for Mycobacterium bovis, the causative agent of bovine tuberculosis, which triggered interleukin 1β (IL-1β) in J774A.1 macrophages via the AIM2 inflammasome." (PMID 40356602, 2025).
bronchiolitis obliterans (2 papers, 2021 to 2022). "In addition, bronchiolitis obliterans (OB) patients with lung transplant have increased IL-17 and Th17 differentiating cytokines (IL-1β, IL-6, and IL-23) in the BAL fluid compared with the controls." (PMID 33419073, 2021).
bronchopneumonia (2 papers, 2014 to 2024). Acute inflammation of the walls of the terminal bronchioles that spreads into the peribronchial alveoli and alveolar ducts. "However, the majority of bronchioles of both IL-1β and IL-1R deficient mice remained inflamed with diffuse bronchopneumonia." (PMID 25198773, 2014).
Calcium oxalate nephrolithiasis (2 papers, 2025). The presence of calcium- and oxalate-containing calculi (stones) in the kidneys. "While both IL-6 and IL-1β are canonical pro-inflammatory cytokines, their mechanistic roles in Calcium Oxalate Nephrolithiasis exhibit distinct divergence." (PMID 41019076, 2025). "At the regulatory level of pro-inflammatory cytokines, interleukin-1β (IL-1β) and interleukin-6 (IL-6), as core mediators of inflammatory responses, play pivotal regulatory roles in Calcium Oxalate Nephrolithiasis formation." (PMID 41019076, 2025). "Furthermore, emerging studies suggest that the elevated expression of IL-1β and IL-6 in Calcium Oxalate Nephrolithiasis may also depend on NF-κB and MAPK signaling pathway regulation." (PMID 41019076, 2025).
carbohydrate metabolism disorder (2 papers, 2022 to 2024). "The results confirmed that there are many markedly altered differences, such as elevated Actinobacteria abundance, plasma IL-1β concentration, lipid, vitamin, and carbohydrate metabolism disorder, and diminished grey matter volume (GMV) of inferior frontal gyrus (IFG) in the MDD patients." (PMID 35013099, 2022). "In diagnosing carbohydrate metabolism disorders, the use of adiponectin, TNF-α, IL-6, resistin, IL-1β and IL-23 in women, and IL-23 in men should be considered." (PMID 39769504, 2024).
cardioembolic stroke (2 papers, 2022 to 2025). "For example, evidence suggests that inflammatory biomarkers like C-reactive protein (CRP), IL (interleukin)-6, IL-1b, TNF-a and D-dimer alongside cardiac biomarkers such as B-type natriuretic peptide (BNP) or its N-terminal fragment, NT-pro-BNP are all associated with cardioembolic stroke." (PMID 40117100, 2025).
carpal tunnel syndrome (2 papers, 2012 to 2013). Entrapment of the median nerve in the wrist that is characterized by numbness, tingling and painful movement. "Overuse upper limb disorders likely involve more injured sites than either WAD or carpal tunnel syndrome resulting in greater concentrations of serum IL-1β." (PMID 24147095, 2013).
cartilage disease (2 papers, 2016 to 2025). Softening and degeneration of the CARTILAGE. "This relatively low number of lncRNAs in common is likely due to differences in conditions (IL‐1β stimulation of chondrocytes versus end‐stage cartilage disease comparison) and methodologic approach (sequencing versus microarrays)." (PMID 27023358, 2016). "This supports the rationale for using ASU beyond cartilage disorders, suggesting that its modulation of IL-1β may also confer protective effects in tendon-healing environments, where inflammation-driven matrix degradation similarly occurs." (PMID 41303871, 2025).
cervical disc degeneration (2 papers, 2014 to 2022). "Based on our data, IL-1β, IL-1R as well as TNF-α might be involved in the pathogenesis of cervical disc degeneration, where IL-1β and IL-1 R might act as better therapeutic targets." (PMID 24804684, 2014).
cervical dysplasia (2 papers, 2014 to 2023). "We have previously shown that the HPV induced cervical dysplasia in patients with decreased serum levels of IFN-γ and IFN-α while increasing the levels of pro-inflammatory cytokines, TNF-α and IL-1β, and cytokine Th-2 type, IL-4." (PMID 24386936, 2014).
Cholera (2 papers, 2019 to 2022). "Two top-scoring targets, Interleukin-1 beta (3rd) and Matrix metalloproteinase-9 (3rd), are related with one top-scoring disease Cholera (4th)." (PMID 35249529, 2022). "To better understand what drives the activation of IL-23 production after exposure to live V. cholerae, we compared its expression and secretion with those of additional cytokines known to be activated in cholera, including IL-1β and IL-6." (PMID 31434744, 2019).
choroidal neovascularization (2 papers, 2012 to 2021). An eye disorder described by the growth of new blood vessels that originate from the choroid through a break in the Bruch membrane into the sub–retinal pigment epithelium (sub-RPE) or subretinal space. "In contrast to the well-documented release of IL-1β in response to RPE para-inflammation there is considerable debate regarding whether IL-18 contributes to or protects from AMD-associated phenotypes including choroidal neovascularization (CNV)." (PMID 34071220, 2021).
chronic GVHD (2 papers, 2025). "We also investigated the incidence of chronic GVHD, OS, EFS, RR, and TRM, as well as the possible influence of the SNPs of IL-1α rs1800587, IL-1β rs1143627, and IL-1β rs16944." (PMID 41291248, 2025).
chronic headache (2 papers, 2014 to 2017). "Acupuncture significantly reduces plasma levels of TNF-α in patients with chronic headache and mRNA levels of IL-6 and IL-1β in rats of lipopolysaccharide-induced fever." (PMID 24991226, 2014).
chronic lymphocytic leukemia (2 papers, 2021 to 2022). "Recent studies suggested that ibrutinib, a Bruton tyrosine kinase (BTK) inhibitor, developed for the treatment of chronic lymphocytic leukemia, may prevent NLRP3 inflammasome activation in macrophages, IL-1β secretion and subsequent development of inflammation and organ fibrosis." (PMID 34099830, 2021).
chronic myelomonocytic leukemia (2 papers, 2021 to 2024). A myelodysplastic/myeloproliferative neoplasm which is characterized by persistent monocytosis, absence of a Philadelphia chromosome and BCR/ABL fusion gene, fewer than 20 percent blasts in the bone marrow and blood, myelodysplasia, and absence of PDGFRA or PDGFRB rearrangement. "This important role of the NLRP3 inflammasome in the pathogenesis of myeloid malignancies and the newly identified KRAS/RAC1/ROS/NLRP3/IL-1β axis has been demonstrated in chronic myelomonocytic leukemia (CMML), juvenile myelomonocytic leukemia (JNNL) and AML patients harboring the KRAS mutation." (PMID 33525345, 2021). "Bryostatin-1 induced proinflammatory cytokines such as IL-8, IL-1β, TNF-α, and IL-6 in human monocytes and increased TNF-α secretion of chronic myelomonocytic leukemia cells." (PMID 39877358, 2024).
Cluster headache (2 papers, 2016 to 2023). A type of headache characterized by repeated attacks of unilateral pain lasting 15 to 180 minutes and associated with local autonomic signs. "Only a single cytokine (IL-1β) was compared between cluster headache and healthy controls in at least two studies, which was not significantly different (SMD 3.36, 95% CI -1.96–8.68, p = 0.22)." (PMID 37016284, 2023).
cocaine use disorder (2 papers, 2022). A substance-related disorder that involves the recurring use of cocaine despite negative consequences. "Our group has described that severity of cocaine consumption is related to IL-1β, SDF-1 and fractalkine in cocaine use disorder patients." (PMID 35625687, 2022).
colonic polyps (2 papers, 2023 to 2024). "Result revealed that both IL-1β precursor as well as mature IL-1β were strongly prevented in small intestinal and colonic polyps." (PMID 37298616, 2023). "Validation by qRT-PCR confirmed increased expression of the LCN2, IL1B, CXCL1, and CXCL3 genes in CCS colonic polyps." (PMID 38297356, 2024).
COPA syndrome (2 papers, 2022 to 2023). "COPA syndrome is associated with autoantibody development, increased Th17 cells and pro-inflammatory cytokine expression including IL-1β and IL-6." (PMID 37317175, 2023).
Creutzfeldt-Jakob Disease (2 papers, 2015 to 2021). "IL-1β levels were elevated in the cerebrospinal fluid of patients with Creutzfeldt-Jakob Disease (CJD), which raises the importance of clarifying the role of inflammasomes in this pathology, as well as in other prion diseases." (PMID 34751640, 2021). "Increased levels of IL-1β have been reported in the cerebrospinal fluid of patients affected by Creutzfeldt-Jakob disease, as well as in the brain of mice or hamsters inoculated with rodent-adapted scrapie prions." (PMID 25671600, 2015).
Cryptosporidium infection (2 papers, 2016 to 2024). "Finally, we tested the level of secretion of interleukins IL-1β and IL-18, which are involved in the NLRP6 inflammasome, recently described as a key mechanism for enterocyte’s defense against Cryptosporidium infection in a mouse model." (PMID 38189373, 2024).
cystic ovaries (2 papers, 2021 to 2024). "In the present study, we found that TNF, IL6, and IL1B were all involved in the NOD-like receptor signaling pathway, which may provide a new field for Jingshu granules in the treatment of ovarian cysts." (PMID 33623786, 2021).
cysticercosis (2 papers, 2019 to 2025). "Cysticercosis-positive individuals showed positive correlations between CD4 counts and pro-inflammatory cytokines (e.g., TNF-α, IL-1β), contrasting with negative correlations in cysticercosis-negative individuals." (PMID 40046043, 2025).
cystinosis (2 papers, 2022 to 2024). Cystinosis is a metabolic disease characterized by an accumulation of cystine inside the lysosomes, causing damage in different organs and tissues, particularly in the kidneys and eyes. "Accordingly, Il-1β signaling blockade has also been proposed as a potential therapy to improve muscle wasting in a murine model of cystinosis." (PMID 39540998, 2024).
Dengue hemorrhagic fever (2 papers, 2018 to 2020). A serious condition caused by Dengue virus infection. "Increased levels of TNF-α, IL-1β, IL-4, IL-6, IL-8, IL-13, IL-15, macrophage migration inhibitory factor (MIF), and chemokines CCL2, CCL4, CCL5, and CXCL10 (IP-10) among others, have been reported in patients with dengue hemorrhagic fever (DHF) when compared to dengue fever (DF)." (PMID 29986388, 2018).
dependence (2 papers, 2015 to 2025). "Given that AUDIT‐C focuses solely on alcohol intake, while AUDIT includes hazardous use and dependence symptoms, the consistent signal from IL‐1β underscores its relevance to both behavioural and physiological dimensions of alcohol use." (PMID 40955775, 2025).
dermatophytosis (2 papers, 2015 to 2017). A common fungal infection of the stratum corneum of the skin, hair, or nails by a dermatophyte. "In addition, IL-1β has recently been shown to be a key mediator in the IFN-γ-induced control of T. rubrum proliferation in an experimental model of dermatophytosis." (PMID 26300867, 2015).
developmental delay (2 papers, 2021 to 2025). "Further, elevated cord blood levels of IL-1β are associated with impaired cerebral metabolism and developmental delay at 2 years of age and increased systemic IL-1β levels are associated with white matter injury in neonatal piglets exposed to LPS." (PMID 34465372, 2021).
dissection (2 papers, 2020 to 2024). The separation and isolation of tissues for surgical purposes, or for the analysis or study of their structures. "Genetic deletion of IL-1β in a mouse model of TAA has been shown to significantly decrease thoracic aortic dilatation, while mouse models of aortic dissection have demonstrated increased levels of IL-1β in aneurysmal tissue, highlighting a potential role of IL-1β expression in TAA development." (PMID 33081376, 2020).
ductal breast carcinoma (2 papers, 2011 to 2020). "Interestingly, a high level of IL-1β is observed in ductal breast carcinoma, while normal tissue does not show any overexpression of IL-1β." (PMID 31963587, 2020).
dysferlinopathy (2 papers, 2021 to 2025). "Supporting the relevance of inflammasome activation in dysferlinopathy, previous studies have shown increased levels of NLRP3, ASC, active caspase-1, and mature IL-1β in skeletal muscles from dysferlin-deficient (A/J) mice." (PMID 41155239, 2025).
dystocia (2 papers, 2014 to 2016). Slow or difficult obstetric labor or childbirth. "In the present study, dystocia was associated with a greater localized inflammatory response, as characterized by the accumulation of more IL-1β, IL-8 and IL-1α in vaginal mucus 3 weeks postpartum compared with healthy animals." (PMID 25395028, 2014). "Animals that suffered dystocia had increased concentrations of inflammatory mediators IL-8, IL-1β and IL-1α in vaginal mucus 3 weeks postpartum, but they also had more bacteria than normal animals." (PMID 25395028, 2014). "In cows, uterine inflammation was characterized by measurement of IL-6, IL-8, IL-1β, interferon (IFN) γ and TNF-α protein by ELISA in vaginal mucus derived from post-parturient cows presenting dystocia or eutocia." (PMID 27152525, 2016). "The vaginal mucus results showed that the concentration of IL-6 was not increased, in contrast to IL-1β, the concentration of which increased in cows that had presented with dystocia three weeks earlier." (PMID 27152525, 2016).
empyema (2 papers, 2016 to 2021). An accumulation of pus in a body cavity, usually the pleural space. "Interesting, the pleural levels of MIF and IL-1β were significantly higher in empyema compared with CPPE." (PMID 33469074, 2021). "The pleural levels of four cytokines (MIF, MIP-3α, IL-1β, ENA-78) were highest and significantly increased in CPPE/empyema compared with those in other etiologies." (PMID 33469074, 2021). "Among the 40 screened cytokines, we identified two, IL-1β and IL-8, that were present at elevated levels and have previously been reported to increase in CPPE/empyema compared to UPPE15." (PMID 33469074, 2021). "Among the six different types of effusions, the mean concentrations of MIF, MIP-3α, IL-1β, and ENA-78 were highest and most significantly increased in CPPE/empyema relative to those in effusions of other etiologies, including UPPE, other exudates, transudates, and MPE." (PMID 33469074, 2021). "IL-1β levels were also significantly increased in PPE, especially in CPPE/empyema, and had an AUC of 0.847 for identifying nonpurulent CPPE from UPPE in our cohort; this finding is consistent with a previous report." (PMID 33469074, 2021).
esophageal tumor (2 papers, 2018 to 2022). "By contrast, the esophageal tumor size and serum levels of IL-1β, IL-4, IL-13 and tumor necrosis factor-alpha (TNF-α) were not significantly affected by adding açaí to the diet for 35 weeks." (PMID 29966007, 2018).
experimental arthritis (2 papers, 2012 to 2018). ARTHRITIS that is induced in experimental animals. "IL-1β and TNF-α are the main inflammatory cytokines in the body, which play an important role in the pathogenesis of RA or experimental arthritis synovitis." (PMID 29743895, 2018). "Cytokines such as interleukin-1-beta (IL-1β), tumor necrosis factor-alpha (TNF-α), and interleukin-6 (IL-6) have been shown to display potent proinflammatory actions and to contribute to the pathogenesis of RA or experimental arthritis, particularly to cartilage and bone damages." (PMID 22414623, 2012).